FGF8 (fibroblast growth factor 8)
Diseases named in the same sentence as FGF8 in open-access papers (continued):
Sharing a sentence is not in itself a finding about the gene and the disease.
prostate (2 papers, 2003 to 2017). "It is well established that prostate carcinogenesis is adversely modulated by the presence of FGF8, and metastatic and more advanced AIPCs are associated with over expression of FGF843." (PMID 28852180, 2017). "This suggests that the region covered by the FISH probe, and by inference its constituent genes including FGF8, is neither amplified nor displays major rearrangement during prostate carcinogenesis." (PMID 12778074, 2003).
brain disorder (1 paper, 2024). A disease affecting the brain or part of the brain.
cardiovascular disease (1 paper, 2020). "The majority of the inflammatory proteins that were found to be significantly elevated have been associated with increased cardiovascular disease such as, interleukin-5, cluster of differentiation 40 (CD40) and interleukin-1beta31, whilst FGF8 has been more associated with vascular remodeling." (PMID 32179763, 2020).
kidney disease (1 paper, 2025). "Moving forward, investigating how modulating the Shh and FGF8 signaling pathways counteract the effects of WDR19 variants may potentially offer promising therapeutic possibilities for this genetic kidney disease." (PMID 41141533, 2025).
neurodevelopmental disorder (1 paper, 2024). A behavioral and cognitive disorder with onset during the developmental period that involves impaired or aberrant development of intellectual, motor, or social functions. "Moreover, FGF8 efficiently modulates key regulators responsible for several human neurodevelopmental disorders." (PMID 39485283, 2024).
FGF8 also shares sentences with these, for which no sentence is quoted: Anosmia (4 papers); hepatoblastoma (3); renal agenesis (2); ameloblastoma (1); autism spectrum disorder (1); Bacterial infection (1); benign ovarian tumors (1); benign prostatic hypertrophy (1); cardiac hypertrophy (1); craniosynostosis syndromes (1); ductal carcinoma (1); ductal carcinoma in-situ (1); endocrine disorders (1); endometrial cancer (1); gastric adenocarcinoma (1); genetic disorder (1); hypogonadism (1); hypopituitarism (1); infantile spasms (1); inflammation (1); invasive ductal carcinomas (1); keloid (1); leukemia (1); liver cancer (1); lung adenocarcinoma (1); lymph node metastasis (1); mandibulofacial dysostosis (1); megalencephaly (1); Moebius syndrome (1); muscular disorders (1).
A further 18 diseases each share a sentence with FGF8 in 1 paper.